TRPV1 (transient receptor potential cation channel subfamily V member 1)
Diseases named in the same sentence as TRPV1 in open-access papers (continued):
Sharing a sentence is not in itself a finding about the gene and the disease.
Obesity (continued). "Previous studies have discovered that activation of this channel can counteract adipogenesis and obesity, and other research has demonstrated that activation of the PI3K-AKT pathway can regulate TRPV1 expression." (PMID 39104411, 2024). "The inhibitory effect of TRPV1-mediated ARNA on RSNA is likely weakened by HFD intake, contributing to obesity-related renal injury and hypertension." (PMID 37047183, 2023). "In these mice, obesity and hypertension appeared earlier and were more severe than in mice with the knockout of UCP1 or TRPV1 alone." (PMID 35043013, 2022). "A mounting evidence demonstrates that TRPV1 knockout mice are resistant to obesity induced by HFD, suggesting that TRPV1 has a role in maintaing lipid homeostasis." (PMID 36589466, 2022). "It has been reported that the dysfunction of the TRP ion channel (TRPV4, TRPV1, TRPM4, and TRPM) is considered to be related to obesity or diabetes, and these disorders are related to appetite, insulin secretion, and autoimmune response." (PMID 34512754, 2021). "The expression trends of TRPV1 and TRPM4 in the patients with diabetes are similar to the patients with obesity." (PMID 34512754, 2021). "Therefore, TRPV1 could be a potential target for obesity management and drug application." (PMID 32175809, 2020). "TRPV1 has also been reported to play a key role in the regulation of food intake and glucose homoeostasis in WAT during the development of obesity." (PMID 32175809, 2020). "Since limited knowledge exists on the ability of CAP to inhibit obesity in female mice, we set to evaluate the effect of feeding HFD (±0.01% CAP) in WT and TRPV1−/− female mice." (PMID 31197191, 2019). "Experimental animal models of high-fat diet-induced obesity show an increased expression of muscarinic M2 and M3 and purinergic P2X3 receptors in the urothelium and the smooth muscle, as well as the TRPV1 and inducible NO synthase proteins in the urothelium." (PMID 31531184, 2019). "A similar effect of obesity on AEA response has been identified in Zucker rats, where the reduced vasorelaxation to AEA was due to decreased CB1 and TRPV1 contribution, increased AEA degradation, and a decreased ability of AEA to stimulate eNOS." (PMID 27633407, 2016). "When genes regulating TRPV1 expression are knocked down, the expression of UCP1 and LETM1 tends to increase, leading to disturbances in mitochondrial Ca2+ homeostasis in BAT and aggravating obesity." (PMID 40677717, 2025). "On the other hand, TRPV1 has been proven not to be related to the anti-obesity effects but only capsaicin; however, this receptor has shown that it can regulate energy expense and cholesterol metabolism." (PMID 40559396, 2025). "Accumulating evidence has established a connection between obesity-induced complications and transient receptor potential vanilloid type 1 (TRPV1), which serves as a ligand-gated nonselective cation channel." (PMID 38406276, 2024). "TRPV1 is a calcium channel activated by capsaicin and, when activated by agonists, prevents obesity induced by HFD: the effect was abolished in mice lacking this channel." (PMID 38390373, 2023). "Morbidly obese men also showed diminished pain and flare response in the capsaicin skin test, though it is not completely clear if this reflects reduced TRPV1 expression or obesity-induced small sensory fiber neuropathy." (PMID 35890150, 2022). "The capsaicin receptor or TRPV1 is another new member of the ECS extended family; expressed centrally and peripherally in the body, it is correlated to thermogenesis and pain regulation and seems to play a part in obesity and T2D." (PMID 35204820, 2022). "Cumulative experimental evidence showed that expression and/or activity of TRPV1 is increased in metabolic syndromes, such as in atherosclerosis, obesity, hyperlipidemia and NAFLD, indicating that TRPV1 is involved in the signaling pathway that favors fat accumulation." (PMID 36589466, 2022).
Obesity (continued). "Dietary addition of capsaicin promoted WAT browning to fight obesity but did not prevent obesity in TRPV1−/− mice, suggesting that activation of the TRPV1 pathway promotes the interaction between PPARγ and PRDM16 protein to protect against obesity." (PMID 35462933, 2022). "On the other hand, in ageing mice fed HFD, the lack of TRPV1 promotes obesity due to altered energy balance and leptin resistance." (PMID 35455971, 2022). "Moreover, TRPV1 was involved in the regulation of energy intake and glucose homeostasis in WAT during HFD-induced obesity." (PMID 34249940, 2021). "TRPV3 could form heteromeric channels with TRPV1, which also involves in the regulation of adipogenesis and HFD-induced obesity." (PMID 34249940, 2021). "They successfully demonstrated that activation of TRPV1 channels by dietary capsaicin results in the browning of WAT, thus prevent obesity, which implies that TRPV could become a promising new target to combat obesity." (PMID 33530406, 2021). "In addition, we also found that TRP ion channel family genes (TRPV4, TRPV1, TRPM4, and TRPM5) related to obesity or diabetes were highly expressed in HBV-related HCC." (PMID 34512754, 2021). "Recently, TRPV1 has been shown to play a key role in regulating the browning of WAT, which could be a novel strategy to counteract obesity." (PMID 32175809, 2020). "We have previously reported that Trpv1 and Trpv3 mRNAs were significantly decreased, whereas Trpv2 and Trpv4 mRNAs were significantly increased in the white adipose tissue (WAT) of either db/db or diet-induced obesity (DIO) mice." (PMID 33195411, 2020). "Consistently, published works from our laboratory unequivocally suggest that CAP prevents HFD (D12492; 60% calories from fat)-induced obesity in the wild type mice but not in TRPV1−/− mice." (PMID 31197191, 2019). "By contrast, HFD did not impair glucose metabolism in the Trpv1−/− animals, suggesting lack of TRPV1 activity prevents the development of obesity-induced disturbance in glucose metabolism." (PMID 31344877, 2019). "Again, this highlights the lack of fundamental knowledge on the role of TRPV1 in energy homeostasis and therefore the current challenges of targeting TRPV1 for the treatment of obesity." (PMID 30108548, 2018). "The pungent CAP could bind to and maximally activate TRPV1 in vitro and counter HFD-induced obesity in mice." (PMID 30518154, 2018). "In TRPV1-/- mice no reduction was observed in gastric tension receptor mechanosensitivity for the condition of high fat diet-induced obesity." (PMID 28701972, 2017). "Upon consumption of high-fat diet, the oral consumption of capsaicin for 120 days successfully hampered the incidence of obesity in WT mice, but, not in TRPV1 KO mice." (PMID 27455231, 2016). "An understanding of how TRPV1 channels, in gastric vagal afferents, are modulated and how these interactions change in HFD induced obesity may lead to more targeted treatments of obesity." (PMID 26285043, 2015). "In adipose tissue expression of TRPV1 mRNA and protein is reduced in obesity, however, in the whole nodose ganglia TRPV1 mRNA content was not significantly altered in HFD mice." (PMID 26285043, 2015). "When Trpv1−/− mice are young, they show increased levels of activity, at least in some experimental paradigms; at this age, they show no obesity." (PMID 21483038, 2011). "One member of the vanilloid TRP family, TRPV1, mediates the sensing of the carotid body to Th2 cytokines and lysophosphatidic acid, and a member of the melastatin TRP family, TRPM7, is involved in the regulation of obesity-induced hypertension mediated by leptin." (PMID 41226725, 2025). "Initially identified as a capsaicin receptor and heat-activated ion channel that modulates pain and neurogenic inflammation, subsequent studies have found that TRPV1 is expressed on many non-neural sites and plays roles in immunity, vasculature, obesity, and thermogenesis." (PMID 38913071, 2024).
Obesity (continued). "To explore the role of TRPV1-positive afferent renal nerves in obesity-related renal injury, we chronically and specifically activate TRPV1 channels in afferent renal nerves with an intrathecal N-oleoyldopamine (OLDA, an endogenous TRPV1 agonist) injection in the present study." (PMID 37047183, 2023). "It was demonstrated that activation of TRPV1 channels by dietary capsaicin results in the browning of WAT, thus preventing obesity, which implies that TRPV could become a promising new target to combat obesity." (PMID 37564131, 2023). "However, the role of TRPV1-positive afferent renal nerves in obesity-induced renal injury has not been fully delineated." (PMID 37047183, 2023). "In addition, TRPV1-mediated Ca2+ influx inhibits lipid accumulation in white adipose tissue (WAT) by facilitating Ca2+ uptake in adipocytes, thus preventing diet-induced obesity." (PMID 35043013, 2022). "Additionally, the size of TRPV1-positive cells in TSOD mice increased compared with that in non-diabetic controls (Tsumura Suzuki Non-Obesity; TSNO)." (PMID 35199097, 2022). "This study concluded that a lack of TRPV1 protects against diet-induced obesity." (PMID 35890150, 2022). "TRPV1 not only exists in adipose tissue, but also influences the CNS and gastrointestinal tract, which suggests that TRP channels in different tissues may have different effects and that the gut-brain axis may be an approach for obesity treatment." (PMID 34345212, 2021). "Moreover, this obesity animal model was characterized by an increase in CGRP release in response to both concentrations of capsaicin administered, suggesting a greater TRPV1-mediated CGRP release from meningeal afferent nerves likely due to a sensitization of the TRPV1 receptor." (PMID 33716794, 2021). "Furthermore, the lack of TRPV1 promotes obesity and induces leptin and insulin resistance, which in turn, resulted in increased food intake and decreased physical activity." (PMID 32175809, 2020). "However, dietary capsaicin treatment has also been reported to prevent high fat diet (HFD)-induced obesity in wild-type (WT) mice in vivo, but not in TRPV1 knockout mice." (PMID 32175809, 2020). "However, knockout of TRPV1 prevents HFD-treatment-induced obesity and obesity-induced hypertension." (PMID 32175809, 2020). "However, a recent study reported that CAP is able to exert anti-obesity effects regardless of TRPV1 channel activation, as shown in TRPV1 KO mice." (PMID 33276488, 2020). "Anti-obesity effect of CAP has been observed regardless of TRPV1 channel activation." (PMID 32180694, 2020). "In addition, long-term feeding of capsaicin prevented obesity in WT but not in TRPV1-null mice assigned to a high-fat diet, indicating that TRPV1 is directly involved in white adipogenesis and obesity in vivo." (PMID 33613196, 2020). "However, a previously published work suggests that lack of TRPV1 prevents obesity diet (28.5% calories from fat)-induced obesity in mice." (PMID 31197191, 2019). "There are reports that dietary capsaicin may keep humans lean, but no clinical study has been done with regard to the use of TRPV1 antagonists in the treatment or prevention of obesity." (PMID 31344877, 2019). "Taken together these observations support the conclusion that “raised levels of adipokines in wild-type but not TRPV1 knockout mice is in keeping with TRPV1 involvement in stimulating the proinflammatory network that is central to obesity induced hypertension”." (PMID 31344877, 2019). "Furthermore, even though a higher body mass in aged Trpv1−/− mice was not reported previously, the obesity-protective role of TRPV1 channels was proposed and supported by two lines of evidence." (PMID 21483038, 2011). "However, there are other approaches where TRPV1 is not needed to have this anti-obesity activity." (PMID 40559396, 2025).
Obesity (continued). "The exact role of TRPV1 and 5-HT1A in obesity is not yet characterized, and additional research is needed to understand their molecular mechanism of action, as well as in the course of insulin resistance." (PMID 32859125, 2020). "In contrast to this observation, a recent study indicates that lack of TRPV1 accelerates diet (Harlan Teklad TD93075; 55% calories from fat)-induced obesity in mice." (PMID 31197191, 2019). "We have recently shown that the activation of the transient receptor potential vanilloid subfamily 1 (TRPV1) protein by capsaicin (CAP; a TRPV1 agonist) counters high-fat diet (HFD; 60% of calories from fat)-induced obesity without decreasing energy intake in mice housed at ambient temperature." (PMID 39204203, 2024). "In addition to non-clinical studies, the beneficial effects of modulating TRPV1, TRPA1 and TRPC5 channels in obesity, T2D, atherosclerosis and MS have been investigated in a range of clinical trials." (PMID 35455971, 2022). "Also, it is evident from our docking studies that CAP-β-dgluco binds to and activates TRPV1 poorly, which accounts for its lack of effect on countering HFD-induced obesity." (PMID 30518154, 2018).
migraine (86 papers, 2005 to 2026). "The results of the present case-control study and meta-analysis exclude a major role of TRPV1 rs8065080, rs222747, and rs222749 as risk factors for migraine chronification." (PMID 39105976, 2025). "Three studies involving a total of 464 participants (241 EM and 223 CM) were included in the meta-analysis of TRPV1 rs8065080 and the risk of migraine chronification." (PMID 39105976, 2025). "Second, only three common TRPV1 polymorphisms were selected for the case-control study, which were chosen based on their previous investigation in migraine research." (PMID 39105976, 2025). "To this end, we first investigated the association of rs8065080, rs222747, and rs222749 of the TRPV1 gene with migraine chronification in a case-control study of participants with EM and CM." (PMID 39105976, 2025). "Calcitonin gene-related peptide alpha (CALCA) and Transient receptor potential cation channel subfamily V member 1 (TRPV1) genes are associated with the pathogenesis of headaches, particularly migraines." (PMID 40002876, 2025). "In the present study, we aimed not only to confirm the previous association of TRPV1 rs8065080 with migraine chronification but also to extend the knowledge about the role of other TRPV1 SNPs in the transformation of EM to CM." (PMID 39105976, 2025). "In conclusion, the results of the present case-control study and meta-analysis exclude a role of TRPV1 rs8065080, rs222747 and rs222749 as risk factors for migraine chronification." (PMID 39105976, 2025). "Although the rationale for investigating TRPV1 as a central role in the pathophysiology of CM is robust, our results exclude a role of three extensively studied polymorphisms of the TRPV1 gene as risk factors for migraine chronification." (PMID 39105976, 2025). "TRPV1 rs8065080 was associated with an increased risk of migraine in the dominant model (CC + TC vs. TT: ORadj = 1.78, 95% CI = 1.09–2.90, p = 0.025)." (PMID 37303955, 2023). "In migraine patients, TRPV1 rs222741 was associated with both anxiety risk and depression risk in the recessive model [ORadj (95% CI): 2.64 (1.24–5.73), p = 0.012; 1.97 (1.02–3.85), p = 0.046, respectively]." (PMID 37303955, 2023). "Once activated, TRPV1 releases neuropeptides, causing neurogenic inflammation and exerting a vasodilatory effect, which are crucial factors in the generation of migraines." (PMID 37240671, 2023). "We found that the TRP gene polymorphisms in migraine comorbidity of anxiety and depression were different except for TRPV1 rs222741." (PMID 37303955, 2023). "Genetic evidence suggests the involvement of TRPV1 in migraine, as a study conducted in the Spanish population found single nucleotide polymorphisms (SNPs) in the TRPV1 gene in patients with migraine." (PMID 37175602, 2023). "Another genetic study on Spanish migraine patients demonstrated an association between migraine and SNPs of the TRPV-1 and TRPV-3 receptor genes." (PMID 36835524, 2023). "TRPA1 is highly co-expressed with TRPV1 and is associated with familial pain syndrome and umbellulone (a naturally occurring migraine inducer)." (PMID 36831105, 2023). "A recent pilot study searching for predictors of migraine chronification investigated 1911A/G single nucleotide polymorphism (SNP) in the TRPV-1 gene in patients with EM and CM compared to healthy subjects." (PMID 36835524, 2023). "More importantly, we first found that TRPV1 rs222741 was associated with migraine comorbidities both anxiety and depression." (PMID 37303955, 2023). "TRPV1 rs8065080 genotype TT decreased migraine risk compared to wild type CC genotype (ORadj = 0.55, 95% CI = 0.32–0.92, p = 0.025)." (PMID 37303955, 2023). "Single nucleotide polymorphisms associated with the susceptibility for migraine have been identified in genes coding for TRPV1 and TRPV3 but the pathophysiological relations with known migraine mechanisms are yet unclear." (PMID 31948011, 2020).